IL10 (interleukin 10)
Diseases named in the same sentence as IL10 in open-access papers (continued):
Sharing a sentence is not in itself a finding about the gene and the disease.
colitis (continued). "Other bacterial products such as polysaccharide A from nonenterotoxinogenic Bacteroides fragilis also promote expansion of IL-10-producing FoxP3+ Tregs and ameliorate colitis in mice." (PMID 25580435, 2014). "In agreement with the findings in DSS-induced colitis model, administration of B2 beads significantly improved disease pathogenesis in IL-10 knockout (KO) mice with spontaneously developed colitis." (PMID 25127031, 2014). "In an IL-10-deficient model, enterocolitis and tumor formation were dependent on the participation of IFN-γ, as blockage with a neutralizing antibody prevented colitis and cancer in young mice (less than 3 weeks old)." (PMID 24901008, 2014). "In the present study, after the second cycle of colitis, IL-10 levels were decreased in the colon of DSS-treated mice, but L. lactis NCDO 2118 administration prevented this reduction." (PMID 25110521, 2014). "C57BL/6 wild-type and IL-10 knockout mice are considered appropriate models for C. jejuni colonisation and colitis, respectively, suggesting that IL-10 signalling is a key determinant of clinical outcome to C. jejuni." (PMID 24823621, 2014). "Various murine models of colitis-associated cancer (CAC) have elucidated much of the carcinogenic process, such as a genetic model of IL-10-deficient mice that develop spontaneous colitis and colonic neoplasms and a DSS-induced colitis and carcinoma model." (PMID 24901008, 2014). "These cells can suppress inflammation induced by CD4+ CD45RBhi T cells in a T cell transfer model of colitis; and one of the main suppressive mechanisms relies on IL-10 secretion by these cells." (PMID 24711809, 2014). "This is also observed for IL-10-/- mice that normally have spontaneous colitis, but in our animal house only show minor inflammation." (PMID 24416370, 2014). "Knockout mice for IL-2 and IL-10 spontaneously develop colitis, and it was recently documented that IL-19-deficient mice present increased susceptibility to acute DSS-induced colitis." (PMID 24718601, 2014). "In detail, real-time PCR data from colonic tissues showed very high expression levels of proinflammatory IL-17A and IFN-γ mRNA in the colon of colitis mice, as well as an increase in colonic IL-4 and IL-10 mRNA, albeit to a lesser extent." (PMID 25313594, 2014). "In trinitrobenzenesulfonic acid-induced colitis in mice and rats TNFα and IL-10 in the mesenteric fat is increased while leptin and adiponectin release is not altered compared to healthy animals." (PMID 25309544, 2014). "Probiotic VSL#3 decreased colitis severity in an inflammatory bowel disease animal model due to an increased production of IL-10 by generating large numbers of Treg cells in lamina propria." (PMID 25162711, 2014). "Like the CD8/CD28− T cells, the mouse homologs of the human CD8/CXCR3+ T cells (CD8/CD122+) suppressed the development of T cell-transfer colitis via the production of IL-10." (PMID 24502291, 2014). "Topically-delivered lentiviral vectors encoding interleukin-10 safely penetrated local mucosal tissue and had therapeutic benefit in this DSS model of murine colitis." (PMID 24712338, 2014). "Unfortunately, this major bias, related to the early onset of colitis in IL10/Nox1dKO mice, makes the reverse chimera uninformative." (PMID 25014110, 2014). "Lastly, CD8αα+TCRαβ+ cells found in the intraepithelial lymphocytes (IEL) of the small intestine (SI) have IL-10 mediated regulatory abilities and can suppress development of T cell-transfer colitis." (PMID 24502291, 2014). "It has been previously shown that IL-10 production is needed to abrogate Th1 cells–mediated colitis serving as a mediator of regulatory T cell functions." (PMID 24873968, 2014). "In mice, gut Clostridium bacteria are potent inducers of colonic interleukin (IL)-10-producing Foxp3 regulatory T cells (Treg), which play key roles in the prevention of colitis and in systemic immunity." (PMID 24714093, 2014).
colitis (continued). "Administration of systemic IL-10 is sufficient to inhibit inflammation and abrogate experimental colitis models." (PMID 24712338, 2014). "It was previously reported that IL-10 deficient mice developed spontaneous enterocolitis similar to human inflammatory bowel disease, and it was proven that large quantities of IL-10 improved formalin or dextran sulfate sodium (DSS) induced colitis." (PMID 24928272, 2014). "Similar to the results previously obtained in a TNBS-induced colitis mouse model, L. lactis MG1363 FnBPA + pValac:il-10 was also capable of diminishing inflammation in the DSS-induced colitis mouse model." (PMID 25106058, 2014). "The development of spontaneous colitis in IL-10−/− mice is known to be strongly influenced by environmental conditions." (PMID 24491821, 2014). "Induction of IL-10 expression by intestinal helminths has also been shown to have beneficial effects by inhibiting colitis in a murine model of inflammatory bowel disease." (PMID 24787713, 2014). "Elevated IL-17 levels and Th17 cells are found in the intestinal mucosa of CD patients and IL-10-treatment of mice with established colitis suppressed Th17 and Th17/Th1 cell development." (PMID 24722226, 2014). "For example, VSL#3 was shown to induce heat-shock-proteins in intestinal epithelial cells (IEC) or enhance proliferation of IL-10-dependent TGF-β-bearing regulatory T-cells in Th1-dependent murine colitis." (PMID 24722235, 2014). "Consistently with the severity of colitis and epithelial damage, 7- and 12-week old IL10/Nox1dKO mice had a barrier dysfunction characterized by an increased colonic permeability measured with FITC-dextran which worsened with age." (PMID 25014110, 2014). "Concomitantly, there was an increased production of IL-10, an anti-inflammatory cytokine that plays an important role in the protection of colitis." (PMID 24603878, 2014). "Severe colitis was mediated by increased local expression of cytokines (IL-6, IL-10, TNF-α, IFN-γ and IL-17A) and phosphorylation of Leucine-rich repeat kinase 2 (LRRK2)." (PMID 24873968, 2014). "These defects are associated with altered IL-10, CTLA4, GITR and CD103 expression in PP4-deficient Treg cells, and are accompanied by gut inflammation and spontaneous colitis in the CD4cre:PP4f/f mice." (PMID 24904742, 2014). "Further support for TLR4 signalling in T cells has been reported in a model of colitis, where TLR4/IL-10-deficient T cells were more pathogenic, compared with IL-10-deficent cells." (PMID 23345540, 2013). "Mice with selective knockout of IL-10 in Foxp3-expressing cells (IL-10fl/fl × FoxP3-cre) do not develop spontaneous systemic autoimmunity but do develop spontaneous colitis in a similar manner to germline IL-10-knockout animals." (PMID 23755052, 2013). "In contrast, anti-IL-17A monoclonal antibody treatment was demonstrated to aggravate dextran sulfate sodium-induced colitis, and blockade of IL-17A in colitis of IL-10 knockout mice was inefficient in reducing disease unless IL-6 was also neutralized." (PMID 23956763, 2013). "To confirm the histological results, we checked mRNA expression patterns of TNF-α, iNOS and IL-10 in colon tissue obtained from DSS induced colitis mice following administration of CO and LiCl." (PMID 24349609, 2013). "Similar mixed immunophenotypes have been frequently reported during experimental inflammation, such as in spontaneous SAMP1/YitFc ileitis or IL-10-/- colitis." (PMID 23977323, 2013). "The leukocyte infiltration into the mucosa and submucosa of the small intestine of mice with colitis at 6 DPI was associated with increased concentration of IL-6, IL-12p70, IL-10, IL-22 MCP-1 and TNF-α, IL-1β, MPO but lower concentration of IL-17A." (PMID 24167594, 2013). "The interleukin-10 knockout (IL-10−/−) mouse is a commonly used model of spontaneous, microbial-induced colonic inflammation similar to IBD." (PMID 23638009, 2013).
colitis (continued). "The aim of this study is to investigate the effects of IL-10 on prohibitin and the role of prohibitin in intestinal fibrosis of murine colitis." (PMID 23690666, 2013). "In contrast, diets low in ω-6 PUFA and high in ω-3 PUFA decrease spontaneous colitis in IL-10 knockout mice." (PMID 23405155, 2013). "Further, CO ameliorated colitis in IL-10−/− and TCRα−/− mice and therapeutic effects of CO correlated with induction of IL-10." (PMID 24349609, 2013). "To investigate the role of inflammatory factors in DSS-induced colitis, we determined the mRNA levels of IL-1β and IL-10 in the intestinal mucosa by qRT-PCR." (PMID 23874391, 2013). "Daily mucosal administration of recombinant L. lactis secreting IL-10 led to a 50% decrease of the colitis induced by the administration of dextran sodium sulfate (DSS) in mice." (PMID 23876056, 2013). "Lindsay and his colleagues also showed that local IL-10 gene therapy using an adenoviral vector reversed colitis in IL-10−/− mice after intravenous administration." (PMID 24314293, 2013). "IL-10 is an important anti-inflammatory factor secreted by mononuclear cells and macrophages in colitis, which can suppress inflammatory reaction and decrease the secretion of pro-inflammatory cytokines such as IL-1β and TNF-a." (PMID 23874391, 2013). "IL-10 is particularly important for Treg cells at environmental interfaces, as a Treg cell-specific inactivation of IL-10 results in spontaneous colitis, heightened immune-mediated lung hyperreactivity, and increased skin sensitivity." (PMID 23801990, 2013). "Treg cell-derived IL-10 controls Th17 cells and a unique population of T cells displaying features of both Th1 and Th17 cells (Th1 + Th17) in a transfer model of colitis." (PMID 23801990, 2013). "IL-10 gene-knockout mice are known to develop a colitis that resembles IBD, and IL-10 gene and IL-10 receptor mutations have been associated with clinical IBD." (PMID 23766559, 2013). "Currently, loss of ADORA2B is considered to result in down-regulation of IL10 production, with accentuation of colitis." (PMID 23638125, 2013). "In chronic DSS colitis and the IL-10-knockout model of IBD, sympathetic denervation using 6-DOPA exacerbated disease." (PMID 23691339, 2013). "These therapies were chosen to replicate the therapeutic aspects of human CD in IL-10−/− murine model of colitis." (PMID 24027765, 2013). "We injected intraperitoneally plasmids carrying IL-4 or/and IL-10 cDNA into mice with TNBS-induced murine colitis and tested the effects of transgenic expression on TNBS-induced murine colitis." (PMID 24314293, 2013). "Spontaneous colitis in GC-C−/−IL-10−/− animals was significantly more severe relative to GC-C+/+IL-10−/− mice." (PMID 24244444, 2013). "In this study, we investigated the effects of IL-4 or/and IL-10 gene therapy on TNBS-induced murine colitis." (PMID 24314293, 2013). "Experimental colitis, induced by adoptive transfer of IL-17-secreting CD4+ T cells to Rag-deficient mice, can be suppressed by the co-transfer of IL-10-secreting CD4+ T cells." (PMID 23755052, 2013). "Activation of the receptor is thought to regulate cytokine production including IL-10; colitis is reduced in knockout mice suggesting a protective role." (PMID 23638125, 2013). "We noted that guanylin production was reduced in IL-10−/− mice that had histologically mild to moderate colitis and very little goblet cell ablation." (PMID 24244444, 2013). "In this study, we found that LMWH downregulated the levels of IL-1β and IL-10 in colitis mucosa, reduced the shedding of syndecan-1, and ameliorated colitis induced by DSS." (PMID 23874391, 2013). "Colitis in the IL-10−/− mouse is dependent upon the gut microflora, and treatments aimed at changing the gut microflora can significantly attenuate or exacerbate disease." (PMID 23638009, 2013).
colitis (continued). "Colitis in IL-10−/− mice is characterized by substantial inflammatory cell movement into the intestinal mucosa that consists of a variety of cell types including macrophages and neutrophils." (PMID 24244444, 2013). "Local delivery of plasmid carrying IL-10 cDNA ameliorated intestinal inflammation in a chemical acute colitis animal model." (PMID 24314293, 2013). "In contrast, IL-4 and IL-10 transgenic expression prevented colitis histology, i.e., histology of IL-4, IL-10 or their combination-treated colon tissues appeared almost normal, with a low level of infiltrating leukocytes." (PMID 24314293, 2013). "Our data suggests that IL-1 antibody administration is effective also I chronic models of DSS-induced colitis when co-administered with IL-10." (PMID 27785242, 2013). "To assess the effects of IL-4 or/and IL-10 expression on treatment of TNBS-induced murine colitis, we intraperitoneally injected these plasmids into mice and then detected these transgenic expressions in murine colon tissues using qRT-PCR." (PMID 24314293, 2013). "Accordingly regulation of colitis by wildtype Treg can be blocked by anti-CTLA-4 antibody, but CTLA-4-deficient Treg can instead utilize IL-10 to achieve regulation." (PMID 23849743, 2013). "Mice with colitis infected with H. polygyrus had higher concentrations of IL-6, IL-12p70, IL-10, IL-22 and MCP-1 but lower amounts of IL-17A (from 5.4 pg/mL to 3.2 pg/mL) at 6 DPI." (PMID 24167594, 2013). "For example, in DSS induced colitis, EP4 receptor agonist suppresses of colitis induced damage by up regulating IL-10 or through increased mucus secretion." (PMID 23613969, 2013). "Bifidobacterium breve induced IL-10-producing T cells in the large intestine and can suppress T-cell-mediated colitis." (PMID 23772228, 2013). "IL-10, which counteracts effects of proinflammatory cytokines such as tumor necrosis factor alpha (TNFα), prevents colitis in mouse models of human IBD." (PMID 24244309, 2013). "The use of LAB to prevent and treat colitis was performed with a recombinant L. lactis strain producing and delivering IL-10, an anti-inflammatory cytokine, in situ in different mouse models." (PMID 23876056, 2013). "In this study, we demonstrate that intracellular delivery of 11R-VIVIT inhibited expression and secretion of inflammatory cytokines in macrophages and ameliorated active colitis in piroxicam treated Il10−/− mice." (PMID 22479554, 2012). "It is also remarkable that the shift from IL-17A into IFN-γ production in the colonic mucosa of IL-10−/− mice coincided with more severe colitis, spreading of inflammation to the small intestine and deterioration in the clinical status of the animals." (PMID 22400037, 2012). "Commensal and probiotic flora signal in part through TLR9-dependent induction of type I interferons such as IFNαA, which regulates inflammation through induction of IL-10 in adult models of colitis." (PMID 23272193, 2012). "The cyclooxygenase 1 and 2 inhibitor, piroxicam (200 ppm), was added to the diet of 5 weeks old mice for 14 days as a validated approach to accelerate the development and increase the penetrance of colitis in Il10−/− mice." (PMID 22479554, 2012). "We finally show that B. breve ameliorated T cell-dependent colitis in immunocompromised mice via T cell production of IL-10." (PMID 22693446, 2012). "Recently, Mikami and coworkers showed that cotransfer of the mixed Th1/Th17 CD4+ T cells from IL-10−/− with colitis with Th1 CD4+ T cells from CD4+CD45high-induced RAG−/− mice with colitis into RAG−/− mice ameliorate wasting disease." (PMID 22400037, 2012). "We have previously reported that stress response genes are upregulated and tricarboxylic acid cycle genes are downregulated in commensal E. coli from monoassociated IL-10-/- mice with overt histologic colitis compared to E. coli from healthy wild-type mice." (PMID 22880065, 2012).
colitis (continued). "Gdac1 lies adjacent to Cdcs3 and Dssc2, which are colitis loci that were identified and analyzed in B6 vs. C3H IL10-KO mice and dextran sodium sulfate (DSS)-treated wild-type (WT) mice, respectively." (PMID 22970191, 2012). "Of note, uninfected IL-10−/− mice with colitis harbored 4 orders of magnitude higher E. coli counts in their large intestines when compared to healthy wildtype mice." (PMID 22563475, 2012). "Animal models have clearly shown that IL-10 is an important regulator in this context as IL-10 knock-out mice develop chronic intestinal inflammation and IL-10 treatment is effective in several models of experimental colitis." (PMID 21811497, 2012). "Colitis in Il10−/− mice was typically most extensive in the proximal colon, followed by the cecum and rectum; the median area involved in each segment was ≤30%." (PMID 22848611, 2012). "Development of colitis in IL-10−/− appears to be mediated by CD4+ T cells and an uncontrolled Th1 response." (PMID 22400037, 2012). "When H. polygyrus was given to piroxicam-treated IL-10−/− mice, the histological scores of colitis severity were drastically reduced within 14 days." (PMID 23053394, 2012). "Taken together with the data on colitis severity (e.g. histologic scores), these data clearly show that TNF is not required for development of clinically significant severe colitis in Il10−/− mice." (PMID 22848611, 2012). "We next examined fecal Lcn-2 levels in IL-10 KO mice, which are prone to developing spontaneous colitis with the extent of colitis exhibiting great variability in different vivaria." (PMID 22957064, 2012). "We examined the effects of 11R-VIVIT administration on the course of colitis in piroxicam treated Il10−/− mice, a commonly used murine IBD model characterized by increased colonic Il12b expression." (PMID 22479554, 2012). "A molecular survey of the main bacterial groups within the colonic lumen revealed that IL-10−/− mice with colitis harbored significantly higher numbers of enterobacteria, Bacteroides/Prevotella spp." (PMID 22563475, 2012). "Severe colitis also develops when RAG−/− mice are reconstituted with IL-10−/− T cells and treated with piroxicam." (PMID 23053394, 2012). "On the other hand, down-regulation of IL-10 contributes to increased intestinal permeability in colitis." (PMID 23166707, 2012). "By 10 weeks of age, IL-10−/− mice developed a mild colitis, the severity of which reached a plateau at 16 weeks of age." (PMID 22400037, 2012). "Eight-week-old female WT (BL6) and IL-10 KO mice were obtained from Jackson Labs, housed in specific pathogen free conditions, and monitored for colitis development for 12 weeks." (PMID 22957064, 2012). "In the colitis case, natural regulatory T (nTreg) cells would be responsible for IL-10 production in response to the microflora." (PMID 22969768, 2012). "CD4+Foxp3+ Tregs were able to control Th17 and Th17+Th1 cells in an IL-10-dependent manner in mice colitis." (PMID 22032685, 2011). "Previously we have shown that blockade of CXCR3 ligands abrogated spontaneous colitis in IL-10-/- mice." (PMID 21858153, 2011). "Three studies have shown that the ability of different lactobacilli to induce a high ratio of IL-10/IL-12 or IL-10/TNF-α production in immune cells correlates with their capacity to provide significant protection in TNBS induced colitis in mice and rats." (PMID 21995674, 2011). "The growth fraction of the tumor was generally higher in IL-10−/−-induced than in AOM/DSS-colitis-induced carcinomas." (PMID 21799775, 2011). "Those that were upregulated by 1 log fold or higher include IL-9, IL-13, IL-4, IL-17A, IL-5, IL-24, IFN-γ, IL-10, IL-11, and IL-27, many of which are known cytokines involved in the pathogenesis of colitis." (PMID 21365015, 2011).